CD1D (CD1d molecule)
Diseases named in the same sentence as CD1D in open-access papers (continued):
Sharing a sentence is not in itself a finding about the gene and the disease.
tumor (continued). "Surface expression of CD1d on tumour cells is assumed to directly correlate with iNKT cell-mediated cytotoxicity, although this seems to depend on the target cell in question." (PMID 37153585, 2023). "Equally low EC50s were observed in co-cultures of CD1d+ tumor cells and mixed (1:1) type 1 NKT/Vγ9Vδ2-T cells." (PMID 36868236, 2023). "In co-cultures of purified (untouched) Vγ9Vδ2-T cells with either the AML tumor cell line THP-1 or purified (untouched) monocytes (expressing similar levels of CD1d), the CD1d-Vδ2 bsTCE triggered Vγ9Vδ2-T cells to lyse THP-1 cells but not monocytes." (PMID 36868236, 2023). "Through TCR-mediated recognition of the tumour CD1d-lipid complex, iNKT cells can directly promote lysis of the CD1d+ tumour cells." (PMID 37153585, 2023). "Persistence of peripheral blood Vγ9Vδ2-T cells appeared to be further reduced in mice treated with the CD1d-Vδ2 bsTCE, possibly as a result of redistribution to (tumor) tissue, TCR downregulation, or activation-induced cell death." (PMID 36868236, 2023). "So, to strengthen the NKT cell function, the CD1d-antibody fusion protein can be applied to direct NKT cells toward tumor cells." (PMID 37158883, 2023). "NKT cell activation by α-GalCer has some beneficial points, including the rehabilitation of NK- and T-cells in the TME and recruiting their power in targeting the CD1d+ tumor cells, the rapid secretion of a wide range of cytokines, and double impact function." (PMID 37158883, 2023). "In bone marrow mononuclear cells (BMMCs) of patients with MM and AML and PBMCs of patients with CLL total T, type 1 NKT and Vγ9Vδ2-T cell frequencies and tumor cell CD1d expression were assessed." (PMID 36868236, 2023). "Because CD8+ TILs are known to back the enhancement of antitumoral immunity, we explored the abundance of intratumoral degranulation marker CD107a+ CD8+ T cells in CD1d−/− mice nourished with a control or WTMCGEP diet 28 days after tumor challenge." (PMID 37152373, 2023). "According to studies by Metelitsa and Karadimitris, CAR-NKT cells can possess a dual-specific killing ability via CAR- and CD1d-dependent mechanisms, yielding a stronger anti-tumor effect than CAR-T cells and effectively eliminating relapsed lymphoma." (PMID 37596653, 2023). "According to these mouse experiments, human NKT cells also exert cytotoxicity against CD1d molecule-bearing tumor cells via perforin/granzyme." (PMID 36769513, 2023). "In contrast, type II NKT cells, characterized by a more diverse T cell receptor recognizing CD1d-presented lipids, predominantly suppress tumor immunity." (PMID 37143732, 2023). "CD1d is expressed on tumor cells in the majority of patients with MM or chronic lymphocytic leukemia and in a subset of patients with acute myeloid leukemia." (PMID 37501530, 2023). "Some tumour cells highly express CD1d molecules, for example tumours of myelomonocytic and B cell lineage origin as well as some solid tumours, such as glioblastoma." (PMID 37153585, 2023). "Recently, CD1d-antibody fusion proteins were made against tumor antigens like human epidermal growth factor receptor 2 (HER2), carcinoembryonic antigen (CEA), and CD19." (PMID 37158883, 2023). "Immune cell abundance study reveals that B2M and CD1D are both enriched in tumor cells and dendritic cells from patients responding to anti-PD1 immunotherapies." (PMID 37077920, 2023). "Binding EC50 for both CD1d and Vγ9Vδ2-T cells and in vitro functional activity (degranulation and tumor lysis) was identical between humanized and wild-type (WT) CD1d-Vδ2 bsTCE." (PMID 36868236, 2023). "Upon 16-h culture of patient-derived MM, monocytic AML, and CLL tumor samples with CD1d-Vδ2 hu-bsTCE, clear degranulation of patient Vγ9Vδ2-T cells was observed." (PMID 36868236, 2023). "iNKT cells, for example, display direct cytotoxic effects on tumor cells expressing CD1d, and administration of αGalCer as an adjuvant in cancer therapy has shown promising results in mice." (PMID 36976644, 2023).
tumor (continued). "NKT cells can directly kill tumor cells by recognizing the CD1d antigen or by activating NK cells, and the number of NKT cells is positively correlated with OS and RFS of HCC patients." (PMID 35251173, 2022). "Therapeutic efficacy was correlated with the number and function of infiltrating iNKT cells, APC presentation, and tumor CD1d expression." (PMID 35886891, 2022). "Through CD1d dependent and independent means, iNKT cells have been shown to lyse a variety of tumor cells." (PMID 36034226, 2022). "CD1d cross-presentation of tumor-derived glycolipids from the surrounding environment enables iNKT cells to eliminate TAMs and dampen their effects." (PMID 36275727, 2022). "These iNKT cell anti-tumor effector functions on immunosuppressive myelomonocytic cells in the TME are exerted by CD1d-cognate recognition." (PMID 35615083, 2022). "CAR-iNKT cells kill their relevant antigen-expressing tumor cell lines or patient-derived plasma cells in vitro and tumor xenograft models in vivo, maintaining their CD1d-dependent functions." (PMID 35615083, 2022). "The less frequent Vδ3+ γδ T cells were shown to recognize and kill CD1d+ target cells and are activated by annexin A2 ligands on tumor cells that are upregulated under oxidative stress conditions." (PMID 35880177, 2022). "iNKT cells exert their anti-tumor effector functions by modulating in a CD1d-cognate recognition manner immunosuppressive myelomonocytic cells infiltrating the TME." (PMID 35615083, 2022). "Observations in a humanized neuroblastoma mouse model highlight the elimination by the transferred human iNKT cells of CD1d-expressing TAMs, impairing their tumor-supporting activity." (PMID 35615083, 2022). "Their CD1d restriction, tumor tissue tropism, ability to restrict the suppressive TME support their exploitation for advanced adoptive cell therapy to treat solid and hematological malignancies." (PMID 35615083, 2022). "In particular, NKT cells play a crucial role in tumor immunity based on the large amount of IFN-γ these cells produce upon engagement of CD1d-presented lipids." (PMID 36297669, 2022). "Monocytes were shown to be the only CD1d+ leukocytes co-localizing with iNKT cells, suggesting an interaction between these two subsets and their progeny in the tumor microenvironment." (PMID 35163561, 2022). "It has been shown that iNKT cells not only produce cytokines but also effectively kill CD1d positive tumor cell lines." (PMID 33499253, 2021). "The role of iNKT cells in recognizing conserved lipid antigens presented via CD1d, and their ability to orchestrate the anti-tumor immune response through cytokine signaling make them attractive targets for cancer vaccine development." (PMID 34680322, 2021). "The anti-tumor immune response can be further enhanced by using α-GalCer-loaded-DCs or CD1d expressing tumor cells loaded with α-GalCer." (PMID 34680322, 2021). "In each gene of the panel, Tumor QMSP was significantly higher than normal QMSP (CD1D: p < 0.001, KCNK12: p < 0.001, PAX5: p < 0.001)." (PMID 34530906, 2021). "iNKT cells have the capacity to mediate direct cytolytic activity against CD1d positive tumor cells via perforin, granzyme B, and TNF-related apoptosis-inducing ligand (TRAIL) pathways." (PMID 34680322, 2021). "For instance, mouse and human iNKT cells have been shown to react to CD1d-expressing tumor cells, suggesting that tumor cells can generate/uncover and present CD1d-dependent iNKT cell Ags." (PMID 34298791, 2021). "iNKT cells can exert their cytotoxic function by granule exocytosis and kill CD1d expressing tumor directly." (PMID 34936686, 2021). "The overall efficacy of iNKT cell immunotherapy is largely dependent on the number and function of tumor-infiltrating iNKT cells and APCs, and often correlates with the level of CD1d expression on tumor cells." (PMID 34680322, 2021).
tumor (continued). "Over the past decade, several studies have convincingly demonstrated the anti-tumor potential of CD1d-restricted iNKT cells against different solid and hematological tumors." (PMID 33499253, 2021). "Taken together with the studies focused on CD1d expression by tumors, this suggests a role for agents that induce CD1d-mediated antigen presentation as means of enhancing NKT cell-mediated cancer immune surveillance in the tumor microenvironment." (PMID 34072042, 2021). "CD1d-positive U251 cells were intracranially injected with iNKT cells and α-GalCer into mice, and tumor growth was monitored by micro-CT." (PMID 33128583, 2021). "CXCR16 recruits natural killer T (NKT) cells in the tumor microenvironment and kill tumor cells in a CD1d-dependent manner." (PMID 32817793, 2020). "For instance, CD1d-restricted iNKT cells efficiently recognize and kill universal lipid antigens presented on tumor cells." (PMID 32570906, 2020). "Both type I and II NKT cells recognize glycolipid antigens on the CD1d molecule, but their functions in tumor immunity clearly differ." (PMID 32231116, 2020). "Mechanistically, HDAC2 can bind to the promoter of CD1d and HDAC2 knockdown in tumor cells results in a significant increase of CD1d surface expression, thus enhancing CD1d-mediated immune recognition and activation of NKT cells." (PMID 32162275, 2020). "These approaches hold great potential for clinical use, as they promote robust iNKT cell activation and augment anti-tumor efficacy in a CD1d-independent manner." (PMID 32560408, 2020). "Anti-tumor surveillance by iNKT cells has been examined in NKT cell-deficient, CD1d-KO, or Jα18-KO mice." (PMID 32231116, 2020). "NKT cells, a CD1d restricted cell type, play an important role in immunosurveillance, however, their exact anti-tumor activity is not yet fully understood." (PMID 33013928, 2020). "Trichostatin A can also enhance CD1d antigen presentation via abrogating the secretion of IL-10 by tumor cells." (PMID 32162275, 2020). "iNKT cells can mediate potent anti-tumor activity directly by targeting CD1d, as well as indirectly by activating NK cells." (PMID 32231116, 2020). "In general, CD1d− tumor cell lines are resistant to iNKT cells, whereas CD1d+ cell lines, such as Jurkat and U937 cell lines, are susceptible." (PMID 32231116, 2020). "To develop an efficient therapy, we proposed using an all-in-one cell type that expressed tumor antigen as well as CD1d and was simultaneously loaded with the iNKT cell ligand α-GalCer, a cell that we reported as an adjuvant vector cell." (PMID 32231116, 2020). "For preclinical modeling of α-GalCer-mediated anti-tumor therapy, we have demonstrated that prophylactic treatment with α-GalCer in the two CD1d-humanized mouse strains can suppress B16 metastasis." (PMID 31244823, 2019). "In the same study they reported a strong and specific in vitro cytotoxicity of ex vivo-expanded human primary NKT, modified with CAR specific for the ganglioside GD2, against both GD2+ tumor cells as well as CD1d+ M2 macrophages in vitro." (PMID 31212634, 2019). "On day 13, we found that α-GalCer treatment increased the frequency of α-GalCer-CD1d tetramer+ NKT cells in both spleen and tumor, and also had significantly increased in the number of α-GalCer-CD1d tetramer+ NKT cells in the spleen." (PMID 31387637, 2019). "The best characterized NKT cell expresses a semi-invariant TCR and releases high amounts of pro-inflammatory cytokines upon recognition of CD1d molecules, which present lipid antigens on the surface of APCs and tumor cells." (PMID 31428574, 2019). "Because sufficient CD19+CD5+ cells infiltrated in tumour tissues can't be acquired for analysis of distinct CD1d expression levels, we only quantified the frequency of CD19+CD5+ cells in tumour tissues and peripheral blood." (PMID 30467955, 2019).
tumor (continued). "iNKT cells can be activated by direct interaction with tumor cells: CD1d+ tumor cells present endogenous glycolipids via CD1d which is then recognized by the T-cell receptor of iNKT cells leading to perforin/granzyme B or Fas/FasL-mediated cytotoxicity." (PMID 31354710, 2019). "iNKT cells also mediate anti-tumor immunity by direct recognition of tumor cells that express CD1d and via targeting CD1d found on cells within the tumor microenvironment." (PMID 31178868, 2019). "In this context, the tumor Ag N-glycolyl-GM3 has been shown to interact with CD1d to induce moderate human iNKT cell proliferation." (PMID 30822302, 2019). "Endogenous glycolipids are known to activate NKT cells and CD1d expression is observed on tumor cells." (PMID 31143179, 2019). "Upon activation with α-GalCer, type I NKT cells were able to kill CD1d+ tumor cells in a CD1d-dependent manner." (PMID 29535734, 2018). "Subsequent studies have revealed that a large amount of interferon-γ released from activated CD1d-restricted type I NKT cells is pivotal for tumor protection." (PMID 29599785, 2018). "This colocalization resulted in CD1d-dependent killing of TAM that cross-presented tumor-derived glycolipids in vivo." (PMID 29535734, 2018). "When the balance of signals is shifted toward activation, an NKT cell is activated, resulting in cytokine production as well as direct killing of tumor cells in a CD1d-independent manner." (PMID 29535734, 2018). "In the CT26 subcutaneous tumor model, Treg blockade was sufficient to protect against tumor outgrowth in WT type and CD1d−/− mice." (PMID 29520281, 2018). "Chemotherapy alone resulted in an increase in tumor cell CD1d expression, facilitating recognition by iNKT cells." (PMID 30013569, 2018). "There is evidence from murine studies that type I NKT cells can be activated by tumor-derived glycolipids that are cross-presented by APC in the context of CD1d." (PMID 29535734, 2018). "The second is by activation of iNKT cells by other CD1d-expressing cells in the tumor microenvironment (TME)." (PMID 29559971, 2018). "In this indirect system, iNKT cell activation by CD1d-expressing TME cells leads to trans-activation of NK cells and/or killing of immunosuppressive cells like tumor-associated Macrophages (TAMs)." (PMID 29559971, 2018). "The protection was shown to be CD8+ T cell dependent, and CD1d−/− mice had significantly higher numbers of tumor-infiltrating lymphocytes." (PMID 29520281, 2018). "The administration of sulfatide to activate sulfatide-reactive type II NKT cells enhanced tumor growth in a CD1d-dependent manner in a murine colon cancer cell line, CT26, lung metastasis model." (PMID 29520281, 2018). "In a 15-12RM fibrosarcoma tumor model in which tumors show a growth-regression-recurrence pattern, IL-13 had a key role for downregulation of CTLs, and CD1d−/− mice had decreased IL-13 production and resistance to the recurrence." (PMID 29520281, 2018). "Type-I NKT cells can directly destroy tumor cells, especially those expressing CD1d on their surface, by performing cytolysis via perforin, granzyme B, Fas ligand (FasL), and TRAIL." (PMID 29354122, 2017). "These cells (aAVC), NIH3T3 cells for mouse and HEK293 for humans, have been transfected with a CD1d and tumor antigen mRNA and then loaded with α-GalCer." (PMID 28824620, 2017). "With higher expression of CD1d, resulting in higher tumor cell lysis and thereby lower metastasis rates, while lack of CD1d expression in tumors leads to their escape from recognition by NKT cells, and tumor progression in some models." (PMID 29018445, 2017). "CD1d-antitumor fusion proteins represent an attractive tool to redirect at the tumor site the immunoregulatory properties of iNKT cells on the innate and adaptive immune responses." (PMID 29163493, 2017).
tumor (continued). "This preservation of iNKT cell responsiveness allowed multiple injections of the fusion proteins, which greatly enhanced antitumor efficacy of tumor-targeted CD1d as compared to αGalCer/CD1d molecules targeted to an irrelevant tumor antigen." (PMID 29163493, 2017). "CD1d-antitumor proteins were initially validated in vitro for their specific binding to tumor cells expressing the relevant tumor antigen." (PMID 29163493, 2017). "For instance, inoculation (single dose) of allogeneic fibroblasts (used as a vector cell) into which tumor antigen mRNA and CD1d with α-GalCer were introduced led to a long-lasting antitumor response." (PMID 28798749, 2017). "The modulation of CD1d expression in tumor cells provides strong evidence for the critical role of iNKT cells in mounting antitumor immune responses." (PMID 29326711, 2017). "Nonetheless, significant antitumor activity only occurred when the CD1d protein was targeted to a tumor antigen by its fusion to an antibody scFv fragment." (PMID 29163493, 2017). "First, we demonstrated that B16-HER2 tumor cells pre-coated with αGalCer/CD1d-anti-HER2 fusion proteins totally abolished their potency to initiate tumors." (PMID 29163493, 2017). "We first showed conclusively that CD1d+tumor/Gal can induce antigen-specific CD4+ and CD8+ T cell immunity." (PMID 28824620, 2017). "While iNKT cells are best known to potentiate their antitumor effect through enhancing the immunogenic activities of a variety of immune cell subsets, they are capable of themselves recognizing and killing CD1d+ tumor cells." (PMID 29326711, 2017). "With ageing, there is a decline in the number of invariant natural killer T cells (iNKT cells)—innate lymphocytes, which represent <1% of the T cell pool and recognise tumours or infected cells via CD1d-presented glycolipids." (PMID 28751932, 2017). "Tumor cells expressing CD1d are mainly of myelomonocytic and B-cell lineages origin, and very few solid tumors have also been found to be CD1d-positive." (PMID 29018445, 2017). "CD1d assembly in the endoplasmic reticulum (ER) is another potential target for tumor CD1d downregulation." (PMID 29326711, 2017). "iNKT cells were shown to directly recognize and kill various human tumor cell lines in vitro and murine tumors in vitro and in vivo through the recognition of endogenous lipids expressed on CD1d." (PMID 29109728, 2017). "Modulation of iNKT cell function, even when CD1d molecules reach the surface of tumor cells, can contribute to evasion of iNKT surveillance." (PMID 29326711, 2017). "In line with this idea, Type-II NKT cells have been shown to impair tumor immunosurveillance in a CD1d-dependent manner." (PMID 29354122, 2017). "Previous data revealed that the inhibition of class II HDACs alone (MC1568) or together with class I HDACs (TSA and LBH589) can enhance tumor cell CD1d expression and their antigen-presenting capability." (PMID 28177888, 2017). "The CD1d-specific antibody treatment in Nf1+/− mice also increased the survival rate of tumor-bearing mice." (PMID 29354122, 2017). "From this finding, we proposed a strategy using all-in one cell type that expressed tumor antigen as well as CD1d that was loaded with the NKT cell ligand α-GalCer simultaneously, a cell that we reported an adjuvant vector cell." (PMID 28824620, 2017). "It is also possible that the killing of CD1d-expressing tumor cells by activated NKT cells leads to the release of tumor antigens and to their subsequent cross-presentation by DCs." (PMID 28798749, 2017). "Tumor development was associated with the appearance of F4/80+CD11bhighGr1low M2 macrophages that produced the tumor-promoting factors IL-6 and EGF, in a CD1d- and IL-13-dependent manner." (PMID 29375569, 2017). "In fact, the therapeutic strategy using tumor/Gal has been extended to many types of CD1d+ tumor cells, including in our own studies, e.g., B16 melanoma, EL4 thymoma, WEHI3B leukemia, and J558 plasmacytoma." (PMID 28824620, 2017).